TSPAN4 (tetraspanin 4)
Diseases named in the same sentence as TSPAN4 in open-access papers (continued):
Sharing a sentence is not in itself a finding about the gene and the disease.
Cerebral ischemia (1 paper, 2018). Restriction of arterial blood supply to the brain associated with insufficient oxygenation to support the metabolic requirements of the tissue. "Indeed, we found that the high-salt diet-induced F4/80+-vesicles after cerebral ischemia expressed TSPAN4 and integrin α5." (PMID 30589884, 2018).
esophageal squamous cell carcinoma (1 paper, 2024). Esophageal squamous cell carcinoma (ESCC) is a type of esophageal carcinoma (EC) that can affect any part of the esophagus, but is usually located in the upper or middle third. "Overexpression of TSPAN4 in esophageal squamous cell carcinoma (ESCC) cell lines notably promoted resistance to paclitaxel (PTX) by inhibiting cell apoptosis." (PMID 39206093, 2024).
Granuloma (1 paper, 2024). A compact, organized collection of mature mononuclear phagocytes, which may be but is not necessarily accompanied by accessory features such as necrosis. "Given the relevance of angiogenesis to tuberculosis, where anti-angiogenic drugs effectively reduce bacterial burden in granulomas, TSPAN4 may play a role in tuberculosis development." (PMID 38680421, 2024).
liver abscesses (1 paper, 2019). "In addition, overexpression of TSPAN4 in B2p clones caused a loss of the pathogenic phenotype, based on the significantly reduced amoebic liver abscesses formed when injected to gerbils, compared with the respective controls." (PMID 31684194, 2019).
melanoma (1 paper, 2026). A malignant, usually aggressive tumor composed of atypical, neoplastic melanocytes. "Here, we identified a novel regulatory axis in which the membrane-organizing protein tetraspanin-4 (TSPAN4) modulates PD-L1 in melanoma cells." (PMID 41525200, 2026). "Functionally, TSPAN4 knockdown in melanoma cells led to more efficient immune checkpoint blockade through PD-1 on T cells." (PMID 41525200, 2026). "This study identifies TSPAN4 as a negative regulator of PD-L1 at the cell surface of melanoma cells suggesting that targeting TSPAN4 may offer a new therapeutic strategy to enhance immune checkpoint blockade in melanoma and other cancers." (PMID 41525200, 2026).
pancreatic cancer (1 paper, 2025). "In the present study, it was observed that fibroblasts derived from metastatic and primary pancreatic cancer tissues exhibited a notable upregulation of genes associated with migration, including TSPAN4 and ITGA5." (PMID 40443671, 2025). "Utilizing single-cell RNA sequencing and spatial transcriptomics, this study identified migrator-associated genes, including TSPAN4 and ITGA5, as critical regulators of fibroblast function in pancreatic cancer." (PMID 40443671, 2025). "Genetic silencing of TSPAN4 significantly impaired invasive behavior in pancreatic cancer cell models (SW1990/PANC-1)." (PMID 40443671, 2025). "This study explored migrasome-associated fibroblasts, especially TSPAN4 and ITGA5, as key regulators of pancreatic cancer metastasis, aiming to provide new ideas for therapeutic strategies targeting TME." (PMID 40443671, 2025). "TSPAN4+ fibroblasts are key regulators of pancreatic cancer progression, contributing to metastasis, immune suppression, and ECM remodeling." (PMID 40443671, 2025). "Within the migrasome-associated genetic repertoire, TSPAN4 and ITGA5 emerge as critical effectors governing fibroblast activation dynamics and stromal communication networks, particularly within pancreatic tumor ecosystems." (PMID 40443671, 2025). "Our results underscore the critical role of TSPAN4+ fibroblasts in pancreatic cancer." (PMID 40443671, 2025). "In-depth study of the specific mechanisms by which TSPAN4+ fibroblasts regulate immune responses and extracellular matrix remodeling using spatial transcriptomics will be essential for the development of targeted therapeutic strategies against pancreatic cancer." (PMID 40443671, 2025). "Tetraspanin 4 (TSPAN4), a member of the transmembrane 4 superfamily, has emerged as a potential contributor to the pathogenesis of pancreatic cancer." (PMID 40443671, 2025). "The complex distribution of TSPAN4 and ITGA5 likely with pancreatic cancer cell migration, proliferation, and ECM degradation highlights the dynamic interactions between cells that drive pancreatic cancer metastasis." (PMID 40443671, 2025).
renal cell carcinoma (1 paper, 2026). "Here, it is demonstrated that in renal cell carcinoma (RCC) cells, N‐terminal truncation of ITM2B facilitates migrasome swelling through the recruitment of TSPAN4 and promotes migrasome formation." (PMID 41319268, 2026).
tuberculosis (1 paper, 2024). A chronic, recurrent infection caused by the bacterium Mycobacterium tuberculosis. "The specific methylation markers in the TSPAN4 gene, identified in whole blood samples, hold promise for improving tuberculosis diagnosis." (PMID 38680421, 2024). "We have introduced a novel method for detecting the TSPAN4 TSS region (cg04552852 and cg12464638) in whole blood samples, offering an effective means for tuberculosis diagnosis." (PMID 38680421, 2024).
type 2 diabetes (1 paper, 2016). "For example, microarray studies performed on human pancreatic islets isolated from patients with type 2 diabetes and glucose-tolerant controls identified, among other changes, overexpression of ENPP1, TSPAN4, TSPAN8, CSRP1, REG3A and REG3G, genes that were also upregulated with age in our study." (PMID 26699651, 2016).
tumor (20 papers, 2022 to 2026). "Subsequently, we examined the association between TSPAN4 expression and the tumor microenvironment, infiltrating immune cells, and immunophenotype." (PMID 39723210, 2024). "Subsequently, we analyzed the cell-cell interaction (CCI) network and identified significant interactions between malignant cluster 10 and CD8Tex, microglia, and endothelial, suggesting an association between the TSPAN4 high-expression subpopulation and the tumor immune microenvironment." (PMID 39723210, 2024). "Additionally, in tumors like GBMLGG and LUSC, TSPAN4 exhibited significant associations with genomic heterogeneity, underscoring its potential impact on tumor diversity and evolution." (PMID 39723210, 2024). "Notably, TSPAN4 displayed inverse correlation with genomic instability (R=-0.16, p=0.046), implying its involvement in shaping immunologically silent microenvironments via tumor mutational burden regulation." (PMID 40443671, 2025). "Besides, TSPAN4 was highly correlated with tumor-associated macrophages." (PMID 37852963, 2023). "These polarized expression topographies implicate complementary roles in tumor-stromal signaling - TSPAN4 as a focal signaling node versus ITGA5 as a ubiquitous adhesion mediator." (PMID 40443671, 2025). "This phenomenon highlights that TSPAN4+ fibroblasts contribute to tumor immune escape and progression." (PMID 40443671, 2025). "Spatial omics mapping unveiled niche-restricted overexpression of migrasome regulators TSPAN4/ITGA5 within specialized tumor microdomains, prompting systematic interrogation of their metabolic network engagement." (PMID 40443671, 2025). "In the TSPAN4 knockdown assay, knockdown of TSPAN4 significantly reduced the proliferation and migration ability of SW1990 and PANC-1 cells, suggesting that TSPAN4 promotes tumor malignancy by promoting cancer cell migration and invasion." (PMID 40443671, 2025). "HE staining revealed a significant reduction in the number of tumor lung metastases in the sh‐TSPAN4+PBS group compared to that in the sh‐NC+PBS group." (PMID 40056029, 2025). "Prior studies have linked several genes (LGALS8, PTPN12, YTHDC2, APOBEC3G, GPX3, RASA3, and TSPAN4) to immune responses, highlighting the impact of the tumor microenvironment (TME) on DCIS." (PMID 41020869, 2025). "TSPAN4, as a migrasome regulator, plays a crucial role in shaping the immunosuppressive tumor microenvironment in pan-cancer." (PMID 39723210, 2024). "Our analysis of the pan-cancer dataset unveiled aberrant expression patterns of TSPAN4 across various tumor types, highlighting its role as a prognostic factor in several cancers." (PMID 39723210, 2024). "With the exceptions of STAD, TGCT, and PCPG, TSPAN4 exhibited aberrant expression across all tumor tissues relative to their corresponding normal tissues, with up-regulation in 12 tumors and down-regulation in 19 tumors." (PMID 39723210, 2024). "As expected, our analysis uncovered a correlation between TSPAN4 expression the tumor immune microenvironment." (PMID 39723210, 2024). "The relationship between TSPAN4 and tumor heterogeneity, stemness, and the immunosuppressive tumor microenvironment was explored through RNA-seq and scRNA-seq data." (PMID 39723210, 2024). "Herein, we calculated correlations between TSPAN4 expression and tumor genomic heterogeneity in pan-cancer." (PMID 39723210, 2024). "TSPAN4 exhibited dysregulated expression in 31 tumor tissues compared with their corresponding normal tissues, with alterations changes in expression were linked to DNA methylation." (PMID 39723210, 2024). "The overexpression of ITM2B1‐115 resulted in elevated p‐STAT3 levels in tumor tissues; again, this increase could be abolished by TSPAN4 knockdown." (PMID 41319268, 2026). "Moreover, IHC revealed significantly decreased Ki‐67 and vimentin expression and increased E‐cadherin expression in the tumor tissues of the sh‐TSPAN4+PBS group." (PMID 40056029, 2025).
tumor (continued). "Notably, TSPAN4+ fibroblasts were found to play pivotal roles in shaping the tumor microenvironment by promoting tumor progression, metastasis, immune evasion, and ECM remodeling." (PMID 40443671, 2025). "This investigation systematically examines the pathophysiological contributions of migrasome-associated fibroblast subpopulations to metastatic dissemination in pancreatic malignancies, with particular emphasis on TSPAN4/ITGA5 expression gradients across tumor ecosystem compartments." (PMID 40443671, 2025). "Comprehensive multi-platform profiling identified TSPAN4-positive fibroblasts as critical network hubs within tumor microecosystems, exhibiting mutualistic functional partnerships with innate immune components (macrophages, monocytes) and stromal elements (vascular networks)." (PMID 40443671, 2025). "Furthermore, we observed a robust correlation between TSPAN4 and genomic heterogeneity, stemness, and the tumor microenvironment in TSPAN4-sensitive tumors, particularly in GBMLGG and LUSC." (PMID 39723210, 2024). "The downregulated TSPAN4 was able to inhibit gastric cancer tumor formation." (PMID 38748047, 2024). "Analyzing the immune subtypes of samples from different tumor types revealed differences in the expression of TSPAN4, and TSPAN4 gene may participate in tumor progression through different mechanisms." (PMID 37852963, 2023). "In addition, TSPAN4 expression was significantly correlated with GBM patient age, tumor grade, IDH mutation status, 1p/19q co-deletion status, and drug resistance." (PMID 37587203, 2023). "Importantly, this transfer of Flag‐ITM2B1‐115 from tumor cells to macrophages could be effectively intercepted by knocking down TSPAN4 in tumor cells." (PMID 41319268, 2026). "In addition, our results show that MFGE8 and TSPAN4 are highly expressed in OS tissues compared to corresponding non‐tumor tissues, and are highly expressed in lung metastatic tissues compared to corresponding tumor tissues." (PMID 40056029, 2025). "Furthermore, the development of therapeutic strategies targeting TSPAN4 may block tumor progression and metastasis and enhance the efficacy of existing immunotherapies." (PMID 40443671, 2025). "Importantly, TSPAN4 expression correlated with immunoregulatory and immune checkpoint molecules, and it regulated immune cell infiltration and modulated immune cell function within the tumor microenvironment." (PMID 39723210, 2024). "However, whether TSPAN4 exerts a similar role in other tumor types, particularly in LUSC, remains unclear and requires further experimental validation." (PMID 39723210, 2024). "Furthermore, gene-editing technologies such as CRISPR/Cas9, or the application of small-molecule inhibitors to disrupt TSPAN4–integrin interactions, may enhance the efficacy of current immunotherapies by overcoming resistance mechanisms and modifying the tumor immune microenvironment." (PMID 40443671, 2025). "Spatial interdependency analyses uncovered microdomain colocalization patterns between TSPAN4+ fibroblasts and CX3CR1+ monocytic derivatives at tumor invasion zones." (PMID 40443671, 2025). "Our investigation into TSPAN4 and CD151’s mRNA expression across different cancers highlighted their elevated levels in tumours, with CD151 consistently surpassing TSPAN4 across various tissues." (PMID 38840183, 2024). "The functional similarities shared by CD151 and TSPAN4, both belonging to the four-transmembrane protein family, elucidate CD151’s comparable labelling effect in tumour cells, where its expression significantly surpasses that of TSPAN4 in pan-cancer contexts." (PMID 38840183, 2024). "Moreover, five genes, including the SLC12A4, SLIT3, GYPC, TSPAN4, CYYBRD1, CYB5R3, and FBLN5 were identified as co-expressed in the healthy and tumor tissue groups." (PMID 37365287, 2023).
tumor (continued). "CD9 (Tspan4) and CD81 (Tspan28), depending on tumor type, can promote or suppress disease progression, while some other Tspan proteins, such as CD82 (Tspan27) and CD63 (Tspan30), have solely been established as tumor suppressors." (PMID 36143328, 2022).
cancer (16 papers, 2015 to 2026). A tumor composed of atypical neoplastic, often pleomorphic cells that invade other tissues. "The migratory marker protein TSPAN4 is highly expressed in various cancers and is associated with cancer invasion and migration." (PMID 36612129, 2022). "TSPAN4 expression differs significantly in immune subtypes of cancers, which can be a diagnostic and prognostic target of cancers due to the high accuracy." (PMID 36685274, 2022). "Among them, TSPAN4 has been confirmed to be associated with the prognosis of a variety of cancers." (PMID 40443671, 2025). "Notably, we observed alterations in DNA methylation levels of the TSPAN4 promoter region, which were associated with its dysregulated expression in pan-cancer, indicating a potential epigenetic regulatory mechanism underlying TSPAN4 dysregulation." (PMID 39723210, 2024). "In addition, the TSPAN4 and migrasomes in macrophages associated with myocardial infarction and pan-cancer progression may be key to the treatment of patients with cardiovascular disease." (PMID 38748047, 2024). "Clinically, TSPAN4-targeted antibodies can enrich migrasomes from plasma, enabling non-invasive cancer monitoring." (PMID 40299331, 2025). "Our study offers comprehensive insights into the role of TSPAN4 in cancer biology, highlighting its potential as a prognostic marker across diverse cancer types, along with its significance as a target for immunotherapy." (PMID 39723210, 2024). "We analyzed TSPAN4 expression and its prognostic significance across multiple cancers using TCGA Pan-Cancer (PANCAN), and TCGA TARGET GTEx datasets." (PMID 39723210, 2024). "Thus, altered DNA methylation might underlie the aberrant expression of TSPAN4 in pan-cancer." (PMID 39723210, 2024). "The results showed that ITGA5, NDST1, CPQ, ITGB1, PIGK, EOGT, and TSPAN4 had amplifications or deletions in most cancers." (PMID 36405728, 2022). "While TSPAN4 has previously been confirmed to play roles in diverse biological processes, including cancer development and the formation of migrasome formation, whether it also contributes to the development of cardiovascular diseases remains unknown." (PMID 41004162, 2025). "In this study, we comprehensively analyzed the expression and function of TSPAN4 in pan-cancer." (PMID 39723210, 2024). "To sum up, we can guess that TSPAN4 of migrasomes may be a highly promising therapeutic target for some cancers." (PMID 38748047, 2024). "However, research into the role of TSPAN4 in cancer remains largely uncharted territory and awaits further exploration." (PMID 39723210, 2024). "TSPAN4 has pan-cancer significance in most cancer types according to bioinformatics analysis." (PMID 36612129, 2022). "DEGs between TSPAN4 high and low expression groups were also explored to validate whether TSPAN4 can be the crosstalk between MI and cancer progression." (PMID 36685274, 2022). "Therefore, it can be speculated from above that the investigation of TSPAN4 functions for GBM treatment may help understand migrasomes in cancer." (PMID 38748047, 2024). "Therefore, we analyzed the expression of TSPAN4 in the pan-cancer dataset (TCGA TARGET GTEx)." (PMID 39723210, 2024). "In addition, TSPAN4 was significantly differentially expressed in different cancers." (PMID 37752917, 2023). "Moreover, there was a correlation between TSPAN4 and cancer treatment-related drugs." (PMID 37752917, 2023). "Therefore, TSPAN4 may be a biomarker and a potential therapeutic target for some cancers." (PMID 36612129, 2022).
cardiovascular diseases (1 paper, 2025). "Vascular smooth muscle cell (VSMC) phenotypic switching is a pivotal driver of intimal hyperplasia in cardiovascular diseases; however, the role of tetraspanin family proteins, such as TSPAN4, in this process remains unexplored and warrants mechanistic investigations." (PMID 41004162, 2025).
infection (1 paper, 2025). The state of being infected such as from the introduction of a foreign agent such as serum, vaccine, antigenic substance or organism. "To determine the cellular functions of TSPAN4 in VSMCs in vitro, we generated stable lines with either TSPAN4 overexpression or knockdown using lentiviral infection." (PMID 41004162, 2025).
kidney diseases (1 paper, 2025). "This increase in the TSPAN4-migrasome signal may be related to the deterioration of podocyte integrity, whereas the decrease in the signal in the advanced stages of kidney disease may mirror the progressive loss of podocytes, given that most urinary migrasomes are of podocyte origin." (PMID 40873806, 2025). "The TSPAN4-migrasome signal was also shown to be a marker for distinguishing patients with kidney disease from healthy controls via receiver operating characteristic curve analysis." (PMID 40873806, 2025). "Similarly, the TSPAN4-migrasome signal was elevated in patients with kidney disease with normal eGFRs (>90 ml/min/1.73 m2) and 24-h urine protein levels (<150 mg) compared with healthy controls." (PMID 40873806, 2025). "Furthermore, the TSPAN4-migrasome signal was increased in patients with diabetic nephropathy, membranous nephropathy, focal segmental glomerulosclerosis, and other kidney diseases compared with healthy controls." (PMID 40873806, 2025). "Similarly, the TSPAN4-migrasome (500–3000 nm) concentration was increased in a cohort of patients with varying kidney diseases diagnosed by renal puncture biopsy, irrespective of eGFR or 24-h proteinuria, compared with healthy controls." (PMID 40873806, 2025). "However, the TSPAN4-migrasome signal did not allow for differentiation among patients with different kidney diseases." (PMID 40873806, 2025).
TSPAN4 also shares sentences with these, for which no sentence is quoted: Alzheimer disease (1 paper); anaplastic ependymoma (1); Astrocytoma (1); cyst (1); esophageal cancer (1); graft versus host disease (1); Hypertension (1); lung carcinoma (1); metastatic cancers (1); non-small cell lung carcinoma (1); oligodendroglioma (1); pancreatic adenocarcinoma (1); proliferative vitreoretinopathy (1); retinal detachment (1); type 1 diabetes (1).